DNMT3B (DNA methyltransferase 3 beta)
Diseases named in the same sentence as DNMT3B in open-access papers (continued):
Sharing a sentence is not in itself a finding about the gene and the disease.
gastric cancer (38 papers, 2008 to 2025). A primary or metastatic malignant neoplasm involving the stomach. "LMP2A up-regulates the expression of DNMT1 and DNMT3B in EBV-associated gastric carcinoma (latency I)." (PMID 32841292, 2020). "The correlation of DNMT3B-579G>T polymorphism with gastric cancer has been identified in different ethnic groups." (PMID 31565203, 2019). "Our current study showed that DNMT3b variants contributed to the long-term survival of gastric cancer." (PMID 26262893, 2015). "Taken together, all these findings demonstrated the predictive value of DNMT3b polymorphisms for the progression and survival prognosis in patients with gastric cancer." (PMID 26262893, 2015). "As far as we know, this is the first report describing the association between DNMT3b polymorphism and gastric cancer survival in a Chinese population." (PMID 26262893, 2015). "We further for the first time investigated the association between DNMT3b polymorphisms and clinical characteristics of gastric cancer patients." (PMID 26262893, 2015). "This study aimed to investigate the association between single nucleotide polymorphisms (SNPs) of the DNMT3b gene and susceptibility and prognosis of gastric cancer." (PMID 26262893, 2015). "In the present study, we systematically explored the role of variants of DNMT3b gene in the development and prognosis of gastric cancer in a large population." (PMID 26262893, 2015). "In the present study, we examined the association between polymorphisms of DNMT3b gene and susceptibility of gastric cancer as well as gastric atrophy, and clinicopathological features and overall survival of gastric cancer in a Chinese population." (PMID 26262893, 2015). "Another polymorphism of DNMT3B, rs2424909, being in great LD with rs2424913 has been found to be a genetic risk factor of gastric cancer, CRCs, and gallbladder carcinoma." (PMID 23666104, 2013). "The polymorphism in the DNMT3B promoter that plays a role in de novo methylation has also been reported to be associated with several tumour susceptibilities, including gastric cancer." (PMID 20128888, 2010). "Meta-analysis of the association of DNMT3B(rs1569686) polymorphism with risk of gastric cancer." (PMID 37878642, 2023). "ORs and 95% CIs of DNMT3b polymorphisms for gastric atrophy and gastric cancer." (PMID 26262893, 2015). "In summary, we find polymorphisms of DNMT3b may affect the overall survival of gastric cancer, suggesting the potential of DNMT3b SNPs as a useful marker to predict overall survival of gastric cancer, especially in patients surviving longer than two years." (PMID 26262893, 2015). "This study provides evidence that DNMT3b polymorphisms may predict long-term survival of gastric cancer." (PMID 26262893, 2015). "Association between DNMT3b polymorphisms and OS of gastric cancer." (PMID 26262893, 2015). "Furthermore, we observed that DNMT3b polymorphisms affect long-term survival of gastric cancer and the effect was even stronger in patients living longer than two years." (PMID 26262893, 2015). "The underlying mechanism of DNMT3b on gastric cancer needs to be clarified in future studies." (PMID 26262893, 2015). "Therefore, more studies may be needed to conclude the role of genetic polymorphism of DNMT3b in the development of gastric cancer." (PMID 26262893, 2015). "In gastric cancer, DNMT3B promotes tumor progression by methylating the MYH11 gene, thereby decreasing its expression and allowing the increase of TNFRSF14, which supports cancer development." (PMID 39185313, 2024). "Their findings also revealed that the DNMT3B upregulation in conjunction with cisplatin treatment significantly increased the apoptotic rate of these resistant gastric cancer cells." (PMID 37705098, 2023).
gastric cancer (continued). "Previous studies also showed that LINC00240 promoted the proliferation, migration, and EMT of gastric cancer cells through the miR-124-3p/DNMT3B axis; lncRNA LINC00240 inhibited the invasion and migration of non-small-cell lung cancer by sponging miR-7-5p." (PMID 36262998, 2022). "Multiple studies showed that DNMT3B acted as an oncogene in tumorigenesis, including acute myeloid leukemia, gastric cancer, bladder cancer, and prostate cancer." (PMID 35812757, 2022). "A meta-analysis in gastric cancer suggested that rs16999593 in DNMT1 and rs1550117 in DNMT3A could contribute to GC risk and that rs1569686 in DNMT3B might be a protective factor." (PMID 35965507, 2022). "LncRNA CCAT2 promotes gastric cancer proliferation and invasion through regulating the E-cadherin and LATS2.And LINC00240 promotes GC tumorigenesis via a LINC00240/miR-124-3p/DNMT3B axis as an oncogene, so it may be a potential diagnostic biomarker for GC." (PMID 34422902, 2021). "The positive correlations between DNMT3A/DNMT3B with PTGS2 was validated in an independent gastric cancer cohort (GSE27342)." (PMID 31534549, 2019). "Another study attributed the genome-wide promoter methylation in EBV driven gastric cancer to the induced expression of DNA methyltransferase-3b (DNMT3b)." (PMID 30151354, 2018). "Nonetheless, role of DNMT3b on gastric cancer will be revaluated and updated in future as the follow-up is still ongoing." (PMID 26262893, 2015). "Our previous work showed that DNMT3b expressed significantly higher in gastric cancer tissue compared to that of the paired control samples." (PMID 26262893, 2015). "Our results suggest that the mechanism that accounts for Ndrg2 methylation in H. pylori-related gastric cancer is elevated DNMT activity secondary to the up-regulation of DNMT3b." (PMID 25823664, 2015). "The data of qRT-PCR showed significant increase in expression levels of both BCL2 and DNMT3B genes in gastric cancer tissue." (PMID 26172537, 2015). "DNMT3b expression was evaluated in cancerous tissue of 104 gastric cancer cases using immunohistochemical method." (PMID 26262893, 2015). "Further investigations are needed to fully clarify the role of the DNMT3b on gastric cancer in different ethnic populations." (PMID 26262893, 2015). "It was revealed that DNMT3B gene is responsible for de novo methylation during embryogenesis and promotes tumor genesis of gastric cancer." (PMID 26172537, 2015). "We found that H. pylori silenced Ndrg2 by activating the NF-κB pathway and up-regulating DNMT3b, promoting gastric cancer progression." (PMID 25823664, 2015). "Emerging studies found that the levels of DNMT1, DNMT3A, and DNMT3B mRNA are reportedly increased in various malignancies, including colorectal, liver, and gastric cancers." (PMID 19638978, 2009). "Additionally, DNMT3B upregulation through the utilization of a DNMT3B plasmid enhanced the sensitivity of gastric cancer cells with cisplatin resistance to cisplatin-induced cell death." (PMID 37705098, 2023). "In addition, PGE2-induced DNMT3B expression and, thus, altered DNA methylation was also reported in gastric cancer, and the combined inhibition of COX-2 and DNMT inhibited gastric cancer growth both in vitro and in vivo." (PMID 35267528, 2022). "Similarly, it has been indicated that 5-Aza-CdR inhibits the activity of DNMT3a and DNMT3b in gastric cancer cell lines SGC7901 and BGC823 thereby up-regulate tumor suppressor gene RASSF1A." (PMID 34319031, 2021). "Overexpression of DNMT3B that combine CDDP (5 μg/ml) could promote apoptosis rate of gastric cancer cisplatin resistance cells, the apoptosis assay analysis by flow cytometric assay." (PMID 32065219, 2020). "Overexpression of DNMT3B by DNMT3B plasmid could promote cisplatin killing of gastric cancer cisplatin resistance cells." (PMID 32065219, 2020).
gastric cancer (continued). "DNMT3b up-regulation has been observed in gastric cancer, but whether H. pylori infection during gastric cancer progression have any role in regulating its expression is unclear." (PMID 25823664, 2015). "Our results suggested that H. pylori may function as an initiator in the progression of gastric cancer by regulating DNA methyltransferase 3b (DNMT3b)." (PMID 25823664, 2015). "Previous studies have shown the ability of EBV and LMP-2 to upregulate DNMT3b and drive hypermethylation in gastric cancer, however, during infection of B cells from peripheral blood, we have been able to identify demethylation events and there are no changes at the miRNA genomic sites." (PMID 25200074, 2014). "However, as far as we know, no paper was available on the role of DNMT3b polymorphism in the prognosis of gastric cancer." (PMID 26262893, 2015). "However, we did not observe any significant associations between DNMT3b variants and risk of gastric cancer or gastric atrophy." (PMID 26262893, 2015). "Aberrant promoter methylation in various tumour suppressor genes is also involved in human gastric cancer and oesophagus carcinoma and the epigenetic silencing linked this aberrant de novo methylation of CpG islands to the overexpression of the DNMT-3 family (DNMT3A and DNMT3B)." (PMID 20128888, 2010). "It has recently been established that in gastric cancer cells, PGE2 induces DNMT3B expression and activity, which in turn results in a higher level of MGMT promoter methylation." (PMID 33941107, 2021). "Upon comparing EBV-positive AGS gastric cancer cells and EBV-negative AGS gastric cancer cells, it was demonstrated that EBV-positive AGS cells are characterized by enhanced activity of DNMT3b and higher SSTR1 CpG island methylation levels." (PMID 33085037, 2021). "DNMT3A expression in gastric cancer (GC) has only been studied in protein levels and showed a significant overexpression of DNMT3A in tumours while DNMT1 and DNMT3B were only modestly over-expressed." (PMID 20128888, 2010). "Meanwhile, E2F6 suppresses Dnmt3b recruitment to mediate germ-line gene silencing in murine somatic tissues, and downregulates MIR22HG and lncRNA CASC2 participating in laryngocarcinoma and gastric cancer progression, respectively." (PMID 39767802, 2024). "Through the miR-124-3p/DNMT3B axis, LINC00240 can also enhance the metastases of gastric cancer." (PMID 36262998, 2022). "In contrast, the expression of other DNMTs, such as DNMT3b and DNMT1 mRNA, was not affected by autophagy induction or inactivation in two independent gastric cancer cell lines (SGC7901 and BGC823)." (PMID 37477089, 2023).
acute myeloid leukemia (35 papers, 2006 to 2026). Acute myeloid leukemia (AML) is a group of neoplasms arising from precursor cells committed to the myeloid cell-line differentiation. "Previous studies demonstrated that DNMT3B overexpression might be associated with resistance to chemotherapeutics in acute myeloid leukemia and prostate cancer cells." (PMID 38368287, 2024). "On the other hand, Micevic and colleagues evidenced that induction of miR-29a-3p in acute myeloid leukemia and Burkitt’s lymphoma could suppress DNMT3B and subsequently cause promoter hypomethylation of tumor suppressor genes." (PMID 34914337, 2021). "Association of DNMT3B genotypes with the susceptibility to acute myeloid leukemia." (PMID 24069326, 2013). "The first identified example of epi-miRNAs was the miR-29 family members (29a, 29b, and 29c); they regulate the expression of DNMT3A and DNMT3B in lung cancer and acute myeloid leukemia (AML)." (PMID 34281210, 2021). "AGT was negatively related to DNMT3A/DNMT3B in acute myeloid leukemia (LAML) and to DNMT1/DNMT3B in LGG." (PMID 34671200, 2021). "DNMT1 and DNMT3b are found to plays roles in the development of central nervous system, while DNMT3a has important functions in acute myeloid leukemia." (PMID 32408199, 2020). "This point was already addressed by others who demonstrated that downregulation of DNMT3A and DNMT3B led to regulation of ESR1 or ESR2 via promoter DNA aberrant methylation in acute myeloid leukemia, endometriosis, prostate and ovarian cancer." (PMID 23626723, 2013). "Overexpression or enhanced catalytic activity of DNMT1, DNMT3a, and DNMT3b has been observed in multiple cancers, including acute myeloid leukemia (AML), chronic myeloid leukemia (CML), glioma, and breast, gastric, colorectal, hepatocellular, pancreatic, prostate, and lung cancers." (PMID 33572577, 2021). "By contrast, deletion of DNMT3A and DNMT3B in mouse hematopoietic stem cells impaired stem cell self renewal, the frequent DNMT3A mutations may be an parts of pathogenesis in acute myeloid leukemia." (PMID 23305405, 2013). "In adult hematopoietic cells and acute myeloid leukemia (AML) cells, the DNMT3B gene is expressed, but the dominant isoform is DNMT3B3, which does not contain part of the DNA methyltransferase domain." (PMID 38295174, 2024). "DNMT1, DNMT3A, and DNMT3B are overexpressed across several types of cancer lineages, including acute myeloid leukemia (AML), melanoma, breast cancer, colorectal cancer, prostate cancer, and stomach cancer." (PMID 36329185, 2022). "In acute myeloid leukemia (AML) for example, Dnmt3b deletion led to accelerated progression in an MLL-AF9 driven mouse model." (PMID 40241199, 2025). "Other studies have reported the overexpression of MYB, DNMT3B, and MYCN in acute myeloid leukaemia patients." (PMID 40911615, 2025). "Together with other DNMTs, DNMT1 was substantially overexpressed in leukemia cells specifically according to leukemia type; likewise, acute myeloid leukemia (AML) cells with methylated p15(INAK4B) expressed higher levels of DNMT1 and DNMT3B." (PMID 36614080, 2022). "And interestingly, miR-29 family reverted global gene methylation by targeting DNMT3a and DNMT3b directly in non-small-cell lung cancer (NSCLC) and acute myeloid leukemia cells." (PMID 29849932, 2018). "Interestingly, in the case of HOTAIR, it was shown to activate methylation at the PTEN locus by upregulating the expression of DNMT3b, thereby promoting resistance to adriamycin (ADM) in acute myeloid leukemia." (PMID 40149464, 2025). "Here, we characterize the DNA methylation phenotypes of bone marrow cells from mice with hematopoietic deficiency of Dnmt3a or Dnmt3b (or both enzymes) or expressing the dominant-negative Dnmt3aR878H mutation [R882H in humans; the most common DNMT3A mutation found in acute myeloid leukemia (AML)]." (PMID 38295174, 2024).
acute myeloid leukemia (continued). "For instance, lncRNA HOTAIR was shown to recruit DNMT3B to increase HOXA5 promoter methylation and silence its expression in acute myeloid leukemia (AML)." (PMID 36533073, 2022).
prostate carcinoma (35 papers, 2007 to 2025). A carcinoma that arises from epithelial cells of the prostate gland. "DNMT3B mutations are more rarely reported in cancer but are seen in advanced prostate cancers displaying a CpG island methylator phenotype." (PMID 39446312, 2024). "A recent, very promising study showed that the overexpression of DNMT1 and DNMT3B is highly linked to the genome-wide hypermethylation profile in prostate cancer and paved the way for studying their function in many malignances." (PMID 37894317, 2023). "DNMT3B (corresponding eQTL rs11480453) encodes a DNA methyltransferase which is thought to function in de novo methylation and have been implicated in prostate cancer development." (PMID 32226005, 2020). "There are five members in the DNMT family, including DNMT1, DNMT2, DNMT3a, DNMT3b, and DNMT3L, the most common mutation of DNMT in cancer is the DNMT3a mutation, while DNMT3b is a pro-carcinogenic gene in endometrial, lung and prostate cancer, and a tumor suppressor gene (TSG) in lymphoma." (PMID 38200495, 2024). "However, two mutations of DNMT3B’s ADD have been observed in prostate cancer, E515D and R545C." (PMID 39446312, 2024). "Downregulation of DNMT3B by miR-145 was achieved through direct targeting, and DNMT3B knockdown increased expression of miR-145 by CpG island promoter hypomethylation, consequently sensitizing prostate cancer cells to radiation." (PMID 41369374, 2025). "Harmine competitively binds to the SAM-binding site of the adenine domain in DNMT3B, thereby inhibiting the activity of the DNMT3B-3L complex and limiting prostate cancer cell proliferation." (PMID 38590646, 2024). "Our investigation into the impact of siRNA-mediated targeting of DNMTs (NDMT1, DNMT3A, and DNMT3B) on SPDEF expression in prostate cancer cells has yielded valuable insights." (PMID 37900138, 2023). "It has been reported that DNMT3b is upregulated and miR-145 is downregulated in prostate cancer cells, and either the repression of DNMT3b or the overexpression of miR-145 can suppress the proliferation and migration of PC3 cells." (PMID 37239435, 2023). "miR-145 overexpression downregulates the expression of DNMT3B; sensitizes prostate cancer cells to X-ray radiation." (PMID 32906681, 2020). "To explore the mechanism of negative regulation of miR‐146a by PVT1, we analyzed the level of three active DNA methyltransferases (DNMT1, DNMT3a, and DNMT3b) in prostate cancer cell lines using qRT‐PCR when PVT1 was aberrantly expressed." (PMID 27794184, 2016). "There was also indication that depletion of DNMT3b resulted in increased apoptosis rate and reduced migration of PC-3 prostate cancer cells." (PMID 22808286, 2012). "It therefore becomes important to understand the function of DNMT3b in silencing of HOXB13 gene in DU145 prostate cancer cells." (PMID 22808286, 2012). "The knockdown of DNMT3B led to the sensitization of prostate cancer cells to radiation." (PMID 33681204, 2021). "Interestingly, the same mutation at position N442K of DNMT3B was identified in two different unrelated ATL patients and has been reported in prostate cancer cells and the Cosmic Database." (PMID 26880370, 2016). "In addition, PVT1 overexpression obviously increased the activity of DNA methyltransferases (DNMT1, DNMT3a, and DNMT3b) in prostate cancer cells." (PMID 27794184, 2016). "The pattern of genomic DNA hypermethylation together with up-regulation of DNMT3b may provide a unique set of biomarkers to specifically identify cadmium-induced human prostate cancers." (PMID 17938735, 2007). "Consistently, DNMT3B could also be induced by irradiation in prostate cancer cells." (PMID 33681204, 2021). "Therefore, anti-cancer agents like mahanine which selectively targets DNMT1 and DNMT3B could be beneficial in prostate cancer therapy." (PMID 24001151, 2013).